HIF1A (hypoxia inducible factor 1 subunit alpha)
Diseases named in the same sentence as HIF1A in open-access papers (continued):
Sharing a sentence is not in itself a finding about the gene and the disease.
metastatic tumors (36 papers, 2007 to 2025). "Chronic diseases such as hepatic cirrhosis, thromboembolic events, and metastatic neoplasms, which were prevalent in group B, are well-documented causes of systemic hypoxia and upregulation of HIF-1α." (PMID 40004007, 2025). "High HIF-1α levels are correlated with high-grade tumours and are associated with early widespread metastatic disease and survival." (PMID 18096060, 2007). "Moreover, β1-integrin interacts with monocarboxylate transporter 4 (MCT4), a transporter associated to lactate export, characteristic among metastatic tumors, whose expression is regulated by hypoxia-inducible factor 1-alpha (HIF-1α)." (PMID 34150624, 2021). "Previous studies discussed additional key factors that led to the stabilization and increased expression of HIF1α in primary and metastatic tumors, such as midkine or LDHA." (PMID 40806669, 2025). "This analysis revealed that SREBF1 and GPNMB were downregulated in metastatic tumor fibroblasts compared to their primary tumor counterparts, and HIF1A was downregulated in metastatic tumor cells compared to primary tumor cells." (PMID 40095604, 2025). "Compared to the ASH1L-low group, lipid-associated TAMs are much more abundant in metastatic tumors expressing high levels of ASH1L, along with enriched HIF-1α transcriptome in cancer cells." (PMID 40394007, 2025). "In the present study, undifferentiated type in primary tumors and HIF-1α high expression in metastatic tumors were the independent prognostic factors in OS." (PMID 32895059, 2020). "Meanwhile, circ-ERBIN knockdown significantly decreased HIF-1α expression in subcutaneous tumors and lung metastatic tumors." (PMID 33225938, 2020). "In multivariate analysis, undifferentiated type (HR 20.873, p = 0.0013) in primary tumors and high HIF-1α expression (HR 2.850, p = 0.0422) in metastatic tumors were independent prognostic factors." (PMID 32895059, 2020). "A phase one trial aimed to investigate whether chronic use of oral topotecan as a single agent suppresses the expression of HIF-1α and angiogenesis in metastatic tumors with the overexpression of HIF-1α (US National Library of Medicine, 2017c)." (PMID 36846589, 2023). "Here we show that Hif1α or Hif2α deletion in the primary tumor decreases metastatic tumor burden in the bone marrow, while Vhl deletion increases bone tumor burden, as hypothesized." (PMID 34556788, 2021). "Univariate analysis of DFS revealed that differentiation type (undifferentiated type, p = 0.0466) and lymph node metastases (positive, p = 0.0146) in primary tumors and grade (B.C, p = 0.0119) and HIF-1α expression (positive, p = 0.0073) in metastatic tumors were significant recurrent factors." (PMID 32895059, 2020). "Univariate analysis of OS revealed that differentiation type (undifferentiated type, p < 0.0001) in primary tumors and H class (2.3, p = 0.0400), grade (B.C, p = 0.0119), and HIF-1α expression (positive, p = 0.0220) in metastatic tumors were significant prognostic factors." (PMID 32895059, 2020). "HIF-1α is highly expressed in a large number of human primary and metastatic tumor tissues." (PMID 27144516, 2016). "However, high levels of HIF-1α protein were observed even in normoxic metastatic tumors with normal expression of wild type PHD2." (PMID 23077544, 2012). "Contrary to that, in the CPTAC samples of the UALCAN database, an insignificant upregulation of HIF-1α protein expression was noted in primary tumours compared to normal kidney tissues, which showed a similar trend in the two in-house matching patient’s primary and metastatic tumours." (PMID 37174052, 2023). "We performed immunohistochemistry for TILs and MCMs (HIF-1α, GLUT1, and PDHK1) in primary and corresponding metastatic tumor tissues." (PMID 41438682, 2025). "The quantitative analysis of GLUT1, HIF-1α, and PDHK1 in primary and metastatic tumors across 26 metastatic PDAC cases was grouped into primary and metastatic categories for pairwise comparison." (PMID 41438682, 2025).
metastatic tumors (continued). "We quantified GLUT1, HIF-1α, and PDHK1 by the QTiS algorithm and found that low expression of GLUT1 in both primary and metastatic tumors correlated with improved OS." (PMID 41438682, 2025). "IHC staining showed significantly increased expression of HIF-1α in circ-ERBIN op subcutaneous tumors and lung metastatic tumors compared with that in control tumors." (PMID 33225938, 2020). "Based on the changes in the expression of HIF-1α, CDK4, and C-Myc in metastatic tumors, we assumed that this regulation is related to ubiquitination degradation." (PMID 32796813, 2020). "HIF-1α plays an important role in tumor angiogenesis and high levels of HIF-1 α can predict an early relapse and metastatic disease." (PMID 26526196, 2015). "Previous research in a similarly sized cohort of patients with paired primary and matched metastatic tumour samples, identified somatic copy number losses at 9p21 (CDKN2A) and 14q (L2HGDH, HIF1A) as critical molecular alterations towards the development of metastatic disease in patients with ccRCC." (PMID 35231161, 2022). "In vivo studies indicated that compared with using DS or HIF-1α knockdown alone, DS with HIF-1α knockdown can better suppress the volume and number of metastatic tumors, and reduce the mRNA and protein expressions of HIF-1α, MMP-2, TGF-β, Twist and N-cad in metastatic tumor tissues of nude mice." (PMID 33976746, 2021). "In humans, the amount of HIF-1α is higher in primary and metastatic neoplasms than in the respective non-neoplastic tissues." (PMID 32375802, 2020). "In both situations, the HIF1-α gene moves to the cell nucleus, promoting VEGFA and PDGFa transcription, As a result many drugs targeting angiogenesis have been developed and are currently being used to treat metastatic disease." (PMID 29202733, 2017). "HIF-1α in primary and metastatic tumors without preoperative therapy positively correlated with leptin (p < 0.0001, r = 0.532; p = 0.013, r = 0.533, respectively) and ObR (p = 0.002, r = 0.319; p = 0.083, r = 0.387, respectively)." (PMID 20569445, 2010). "HIF-1α has been shown to be expressed in most RCC tumors while HIF-2α is relatively absent in early tumors, but is highly expressed in metastatic tumors." (PMID 23374878, 2013).
prostate tumors (36 papers, 2010 to 2023). "Altogether, our findings demonstrate that HIF1A is a key factor for Pten‐deficient luminal cell survival after castration, making HIF1A inhibition a highly attractive approach to overcome castration resistance of prostatic tumors." (PMID 37070472, 2023). "In conclusion, our study demonstrates that HIF1A inhibition overcomes castration resistance in Pten‐deficient prostatic tumors in mice and induces apoptotic signaling in human castration‐resistant cell lines." (PMID 37070472, 2023). "Collectively, these data demonstrate that luminal HIF1A is a key driver of castration resistance in Pten‐deficient prostatic tumors and that its inactivation overcomes this resistance." (PMID 37070472, 2023). "For example, in 100 human primary prostate tumors, HIF-1α expression was associated with treatment failure, disease relapse, and decreased metastasis-free survival and castration-resistant prostate cancer (CRPC)-free survival." (PMID 29497081, 2018). "Our findings provide a possible mechanism for the increased NF-κB activation that is associated with high Gleason grade prostate tumors because these tumors also exhibit loss of ERβ and induction of HIF-1α expression." (PMID 26450901, 2015). "KLF5 loss enhances tumor angiogenesis by attenuating PI3K/AKT signaling and subsequent accumulation of HIF1α in PTEN deficient prostate tumors." (PMID 25896712, 2015). "Importantly, we show that genetic and pharmacological inhibition of HIF1A sensitizes Pten‐deficient prostatic tumors to castration and provides durable therapeutic responses." (PMID 37070472, 2023). "While this effect was concluded to result from the alleviation of AR-mediated repression of Zeb1 expression, androgen depletion-induced EMT could also be driven by HIF-1α, as androgen deprivation caused hypoxia in prostate tumors." (PMID 25821081, 2015). "A significant HIF1A expression has been detected in a large number of cancers, which include among others prostate tumors." (PMID 35252204, 2022). "Hypoxia is a constant characteristic of prostate tumour microenvironment, and HIF‐1α is the key regulator of the transcriptional response to hypoxic stress." (PMID 33025691, 2020). "Deletion of KLF5 can result in a decrease in PI3K/AKT signaling and accumulate HIF1α in prostate tumors to promote tumor angiogenesis." (PMID 31341536, 2019). "The expression of both MTA1 and HIF‐1α at protein and mRNA levels in prostate tumor tissues from mice treated with agents was significantly reduced compared to vehicle controls." (PMID 29024573, 2017). "Collectively, this data demonstrate a more potent MTA1/HIF‐1α‐targeted response to Pter/SAHA combination treatment than to single therapies both in murine prostate tumors and in PCa cell lines." (PMID 29024573, 2017). "We found that in MTA1‐high group, 69.2% showed high levels of HIF‐1α, whereas in MTA1‐low group, 83.3% showed low HIF‐1α, once again indicating positive relationship between MTA1 and HIF‐1α expression in prostate tumors." (PMID 29024573, 2017). "It is known that Hif1α is up-regulated in most prostate tumor tissues, compared with normal and benign prostate tissues." (PMID 26213336, 2015). "We show that MRV downregulates the attractive cancer therapeutic target HIF-1α and induces apoptosis in hypoxic prostate tumor cells." (PMID 24504474, 2014). "Altogether, these data strongly demonstrate that MRV infection interferes with accumulation of active HIF-1α protein in hypoxic prostate tumor cells." (PMID 24504474, 2014). "Taken together, these data indicate that HIF-1α down-regulation in MRV infected hypoxic prostate tumor cells occurs via both proteasome-mediated degradation and inhibition of HIF-1α mRNA translation." (PMID 24504474, 2014). "To determine if HIF-la expression was altered by MRV infection in hypoxic prostate tumor cells, we first performed immunofluorescence assays to examine HIF-1α expression on an individual cell level." (PMID 24504474, 2014).
prostate tumors (continued). "In the current study we have shown that normoxic HIF1α also increases metastatic potential and chemo-resistance in PC cells and HIF1α expressing human prostate tumors have poor outcomes." (PMID 23342109, 2013). "Clinical outcomes were correlated following the staining of 100 prostate tumors for HIF1α expression." (PMID 23342109, 2013). "Our results also suggest that activated Rap1 in prostate tumor cells sensitizes the cells to inhibition of HIF-1α activity by PKA." (PMID 23166790, 2012). "Our results indicate that Rap1 activation in prostate tumor cells promotes angiogenesis under hypoxic-like conditions via HIF-1α and VEGF, and PKA activation antagonizes this induction." (PMID 23166790, 2012). "In summary, our results suggest that cytoplasmic HIF1α in androgen independent NE cells of benign prostate tissue and non NE differentiated prostate tumors, corresponds to HIF1α1.2 isoform." (PMID 20663134, 2010). "One of these isoforms, HIF1α1.2, which was previously reported to be testis specific, was found in 86% of NE-differentiated prostate tumors, 92% of HIF1α immunoreactive prostate tumors and 100% of cases of benign prostate hyperplasia." (PMID 20663134, 2010). "In addition, TLR4 is known to induce VEGF expression in prostate tumors related to interaction with hypoxia inducible factor-1 α (HIF-1α); VEGF enhances the nuclear factor kappa-light-chain-enhancer of activated B cells (NF-κB) in the tumor microenvironment." (PMID 36829917, 2023). "Furthermore, HIF1A silencing in PC‐3 cells enhanced CC3 levels (Fig EV3D), demonstrating that pharmacological inhibition of HIF1A induces profound anticancer effects in castration‐resistant prostate tumor cells." (PMID 37070472, 2023). "Therefore, our data demonstrate that HIF1A in prostatic tumor cells is a critical factor that enables their survival after ADT, and identify it as a target for CRPC management." (PMID 37070472, 2023). "Together, our results suggest that the interplay between miR-182 and HIF1α could result in a sustained activation of HIF1α pathway, which might facilitate tumor cell adaption to hypoxic stress during prostate tumor progression." (PMID 26205124, 2015). "Furthermore, HIF1α is upregulated in prostate tumors 10,11 and is a potent defensive mechanism used by tumor cells against oxidative stress or destruction by androgen deprivation, chemotherapy or radiation cytotoxicity." (PMID 24464861, 2014). "Addition of MG132 to the infected samples from 8–12 h p.i., was able to rescue HIF-1α to levels similar to those seen in uninfected cells; suggesting that MRV infection induces proteasome-mediated degradation of HIF-1α in hypoxic prostate tumor cells at early times p.i." (PMID 24504474, 2014). "Low oxygen in prostate tumors is strongly predictive of relapse after therapy, illustrating the need to identify novel treatment strategies that target hypoxic tumor cells, and the HIF-1α protein that modulates the cellular hypoxic response." (PMID 24504474, 2014). "Thus, HIF-1α is a major regulator of the hypoxic adaptive response of prostatic tumors, which makes HIF-1α a viable target for both chemopreventive and chemotherapeutic strategies." (PMID 24515947, 2014). "However the consensus is that HIF1α is upregulated in prostate tumors and is a potent tumor-induced shield against oxidative stress or destruction by androgen deprivation, chemotherapy or radiation cytotoxicity." (PMID 23342109, 2013). "The significance of the expression of HIF1α in prostate tumors has been investigated previously." (PMID 23342109, 2013). "Thus Prx1 enhanced expression of HIF-1α in endothelial cells in vitro and in prostate tumors in vivo." (PMID 23185615, 2012). "Indeed, in this study, we have shown that a broad range of HIF1α isoforms are present in both benign prostate hyperplasia and prostate tumors." (PMID 20663134, 2010).
prostate tumors (continued). "Collectively, these findings demonstrate that TGM2 expression correlates with HIF1A signaling in mice and human prostatic tumors, has potential prognostic value in predicting relapse in patients with PCa, and may thus be used to guide their clinical management." (PMID 35867798, 2022). "Importantly, equivalent HIF‐1α staining was observed in prostate tumors cultured in three independent laboratories and evaluation of serial sections of individual tissues indicated no discernible difference in histology or antigen staining between the air or sponge interface (data not shown)." (PMID 30117261, 2018). "Thus we hypothesized that MRV induced HIF-1α downregulation in prostate tumor cells may require a functional proteasome." (PMID 24504474, 2014). "Alternatively, more advanced prostate tumors may express differentially HIF1α." (PMID 22546016, 2012). "S5E), these data demonstrate that HIF1A promotes the expression of EZH2 and SOX2 under both hypoxic and normoxic conditions and enhances the progression of prostatic tumors." (PMID 35867798, 2022). "Furthermore, it has been shown that the combination of other pharmacological inhibitors of HIF-1α and STAT3 enhanced prostate tumor growth suppression." (PMID 30347860, 2018). "We confirmed that HIF-1α was remarkably upregulated in human prostate tumors and PCa cell lines, but not in corresponding normal tissues or nonmalignant cells." (PMID 28790395, 2017). "Equal size (150 mm3) PC-3M prostate tumors expressing non-specific shRNA (Scramble) or shRNA specific for Prx1 (shPrx1) were collected and examined for Prx1 and HIF-1α expression." (PMID 23185615, 2012). "We also investigated the localization of HIF1α and HIF1β using immunostaining of serial sections of two cases with NE and non-NE prostate tumors." (PMID 20663134, 2010). "More importantly, prostate tumors lacking HIF-1α expression did not metastasize or develop CRPC11." (PMID 29497081, 2018). "This negative feed-back loop may explain why Hif1α mRNA levels were only altered in an early stage (18 wks) of prostate tumor development in TRAMP.eJag1 mutants since at late stages (24 wks) modulation of Hey1 mRNA levels may have caused a repressive effect." (PMID 26213336, 2015). "However, HIF-1α activity was strongly diminished in MRV-infected compared to mock-infected hypoxic cells, further supporting the conclusion that MRV infection results in diminished levels of active HIF-1α protein in hypoxic prostate tumor cells." (PMID 24504474, 2014).